NANOGNB (NANOG neighbor homeobox)
Tractability: No criterion of Open Targets' tractability assessment is met for any kind of drug.
Gene: Protein-coding gene on chromosome 12 (7,765,216 to 7,774,121, forward strand). Ensembl gene ENSG00000205857.
Subcellular location: Nucleus
Gene Ontology:
Molecular function: DNA-binding transcription factor activity; DNA binding
Biological process: regulation of transcription by RNA polymerase II
Cellular component: nucleus
Genetic constraint (gnomAD): Loss-of-function variants: 12 observed, 12.81 expected, observed/expected ratio (o/e) 0.94, 90% interval 0.6 to 1.51. The upper end of that interval is the gene's LOEUF score, 1.51, which puts it in group 6 of 6, group 1 being the genes least tolerant of losing a copy. Missense variants: 95 observed, 96.36 expected, observed/expected ratio (o/e) 0.99, 90% interval 0.83 to 1.17. Synonymous variants: 37 observed, 31.73 expected, observed/expected ratio (o/e) 1.17, 90% interval 0.9 to 1.53.
Homologues: Orthologues: chimpanzee NANOGNB (97% identical), Drosophila melanogaster Rim (19% identical), zebrafish rims2b (17% identical), Caenorhabditis elegans unc-10 (15% identical). Paralogues in human: RIMS2 (26% identical), RIMS1 (24% identical), RIMS4 (14% identical), RIMS3 (13% identical).
Diseases named in the same sentence as NANOGNB in open-access papers:
NANOGNB is named in the same sentence as 5 diseases in open-access papers, as found by Europe PMC text mining. Sharing a sentence is not in itself a finding about the gene and the disease. The quoted sentences say what the papers report.
cancer (3 papers, 2012 to 2024). A tumor composed of atypical neoplastic, often pleomorphic cells that invade other tissues. "Many of the upregulated genes, i.e., PARP8, ATP6, V1G3, NANOGNB, and CALB1, have been reported to be upregulated in various cancer cells." (PMID 36230929, 2022).
NANOGNB also shares sentences with these, for which no sentence is quoted: atherosclerosis (1 paper); breast carcinoma (1); invasive carcinoma (1); lung carcinoma (1).